IL10 (interleukin 10)
Diseases named in the same sentence as IL10 in open-access papers (continued):
Sharing a sentence is not in itself a finding about the gene and the disease.
distal colitis (3 papers, 2009 to 2023). Particular variety of ulcerative colitis where only the left half of the colon is inflamed. "For example, Enterococcus faecalis induced a slow-onset (10–12 weeks) of distal colon predominant inflammation, which progressed to severe distal colitis and duodenal inflammation by 24 weeks in IL-10−/− mice." (PMID 19841748, 2009). "Inflammation, coagulation and immune indicators like CRP, FC, IL-10, D-D and α1-MG are higher in extensive colitis, and metabolic indicators like LDL-C, HDL-C, TC, GSP and albumin are higher in distal colitis." (PMID 37457023, 2023).
dysentery (3 papers, 2008 to 2025). Acute inflammation of the intestine associated with infectious diarrhea of various etiologies, generally acquired by eating contaminated food containing toxins, biological derived from bacteria or other microorganisms. "B. hyodysenteriae inoculation induced production of systemic levels of IL-1β during the dysentery period and increased levels of IL-10 coincided with recovery from dysentery." (PMID 18700003, 2008). "Blood was sampled before inoculation and repeatedly during acute dysentery and recovery periods and cytokine levels of IL-1β, IL-6, Il-10, TNF-α and IFN-γ were measured by ELISA." (PMID 18700003, 2008). "The aim of the present study was therefore to induce dysentery experimentally in pigs and to monitor the development of some immunoregulatory cytokines (IL-1β, IL-6, Il-10, TNF-α and IFN-γ) in blood collected at various stages of the disease." (PMID 18700003, 2008). "In conclusion, increased levels of the pro-inflammatory cytokine IL-1β and SAA were detected during the period with dysentery, whereas an increase in IL-10 was seen during the recovery period." (PMID 18700003, 2008). "Increased levels of GM-CSF and reduced production of TNF-β, IL-1β, IL-17A, IL-16, IL-4, and IL-10 were distinct responses observed in Shigella-infected children with dysenteric diarrhea compared to Shigella without dysentery." (PMID 35924851, 2022). "Children with dysenteric Shigella had lower levels of IL-16, IL-4, and IL-10 in their stools than children with Shigella without dysentery after adjustment for age and sex (blue circles)." (PMID 35924851, 2022).
dyslipidaemia (3 papers, 2017 to 2020). "Dyslipidaemia can induce the production of inflammatory cytokines, such as interleukin-6 and tumour necrosis factor-α, and reduce the anti- inflammatory cytokines, such as Interleukin-10." (PMID 31752704, 2019).
Ebola (3 papers, 2014 to 2021). "Likewise, the severity of Ebola virus disease was statistically significantly associated with elevated plasma levels of several cytokines and chemokines such as IL-6, IL-8, IL-10, MCP-1 and MIP-1β during the acute phase of infection." (PMID 28106111, 2017). "In contrast to the results of this study, fatal Ebola patients had higher serum IL-10 levels than the survivors." (PMID 25066751, 2014).
echinococcosis (3 papers, 2021 to 2025). A parasitic infection caused by tapeworm larvae of Echinococcus. "Clinical data on the effects of ABZ in echinococcosis patients revealed significant reductions in IL-10 and partial reductions in IL-4 in serum that was associated with the successful therapy." (PMID 40725240, 2025). "Anti-echinococcosis-related cytokines (IL-2, IL-4, IL-10) were significantly increased." (PMID 34488852, 2021). "Indeed, the clinical data in this study further pointed out that host immunity, which is generally characterized by immunosuppression with high-level interleukin 10 (IL-10) expression and Treg cell expansion, as well as T-cell exhaustion during hydatid disease, links to the fungal expansions." (PMID 36098525, 2022). "Thus it could be speculated that IL-10 may play an anti-echinococcosis role by downregulating VEGF expression and inhibiting angiogenesis in the metacestodes." (PMID 34488852, 2021).
egg allergy (3 papers, 2021 to 2024). A food allergy that is an allergy or hypersensitivity to dietary substances from the yolk or whites of eggs, causing an overreaction of the immune system which may lead to severe physical symptoms. "On the other hand, no negative nor positive association was found between IL-10, IFN- γ and TNF-α responses at 4 months of age in children with IgE-mediated hen’s egg allergy at age 12 months." (PMID 36756279, 2023).
endophthalmitis (3 papers, 2023 to 2025). An infectious process affecting the internal structures of the eye. "The opposite direction of the correlation between IL-10 and IL-18 in endophthalmitis and control groups is interesting, as IL-10 is known to be a regulator of IL-18 signalling, and subsequent IFN-γ induction by NK cells." (PMID 40563988, 2025). "In an intradermal infection mice model, IL-1β, IL-6, TNF-α, and IFN-γ were produced by the lymph nodes only after MSSA infection; while in a murine model of endophthalmitis, IL-10, IL-15, IL-11, and some chemokines and receptors were significantly strongly upregulated by MRSA." (PMID 38571946, 2024). "In the vitreous of patients with distinct clinical characteristics, an intensified inflammatory response involving IL-10, IL-6, IL-8, IL-1β, and TNF-α was observed in cases of MDR P. aeruginosa endophthalmitis compared to infections caused by sensitive P. aeruginosa." (PMID 37624004, 2023). "Interestingly, IL-18/IL-10 was also significantly correlated in both groups; however, the correlation was negative in the endophthalmitis group and positive in the controls." (PMID 40563988, 2025).
Epstein-Barr virus infection (3 papers, 2001 to 2019). An infection that is caused by Epstein-Barr virus. "One of the best examples of this is Orf virus-encoded interleukin 10, such as that produced during Epstein Barr virus infection which has been demonstrated to enhance mast cell proliferation, similarly to mammalian IL-10." (PMID 31480219, 2019). "Additionally, the pathway ‘Epstein-Barr virus infection’ was simultaneously enriched, in which several genes including BCL2, CD39, HSP70, HDAC45, IL10, IL10R and vimentin were up-regulated, together with some down-regulated genes such as CD38, NUP214, RBP-Jκ, CycA, TAK1 and TBK1." (PMID 28912500, 2017).
esophageal adenocarcinoma (3 papers, 2020 to 2022). A malignant tumor with glandular differentiation arising predominantly from Barrett mucosa in the lower third of the esophagus. "The profile of mediators in BE provide further understanding of the pathogenesis of Barrett's esophagus and the possible immunoregulatory role of IL-10 associated with the permanent mucosal damage that is unable to counteract the aggression of other inflammation mediators." (PMID 33941087, 2021). "We detected the tissue mRNA expression of IL-1β, IL-4, IL-6, and IL-10 in the esophageal adenocarcinoma rat model." (PMID 36110250, 2022).
extrapulmonary tuberculosis (3 papers, 2009 to 2025). A tuberculosis that occurs at body sites other than the lung. "We have recently reported that the ratio of these two key cytokines (IFNγ/IL10) shows significant correlation with clinical severity in extra-pulmonary tuberculosis,with higher IFNγ/IL10 ratio relating to less severe disease." (PMID 19274101, 2009).
Failure to thrive (3 papers, 2012 to 2024). Failure to thrive (FTT) refers to a child whose physical growth is substantially below the norm. "We conducted this study to investigate the effect of Lf supplementation in ONS on IL-6 and IL-10 levels in children with failure to thrive and infection." (PMID 38434639, 2023). "Here, we investigate the effect of lactoferrin in ONS towards IL-6 and IL-10 in failure to thrive children with infections during a 90-day intervention." (PMID 38434639, 2023). "Our hypothesis is that lactoferrin influences the immune systems of children with failure to thrive and infections, particularly in relation to IL-6 and IL-10." (PMID 38434639, 2023). "Tnf−/−:Il10−/− (T/I) young adult males and females were fertile with normal litter sizes, however pups often exhibited high early mortality and/or failure to thrive." (PMID 22848611, 2012).
fertility disorders (3 papers, 2008 to 2018). "IL-10 was found to be up-regulated in both cervical cells and PBMCs stimulated with incs in CT-positive women with fertility disorders, with levels being significantly higher than CT-positive fertile women and controls." (PMID 19397832, 2009). "Significantly higher levels of IL-1β, IL-6 and IL-10 were detected upon inc-stimulation of cervical cells and PBMCs from CT-positive women with fertility disorders as compared to CT-positive fertile women or controls (P < 0.05)." (PMID 19397832, 2009). "In contrast, IL-1β, IL-4, IL-5, IL-6 and IL-10 mRNA expression levels were significantly higher (P < 0.05) in cells obtained from CT-positive women with fertility disorders compared to other two groups." (PMID 19397832, 2009). "In contrast, IL-1 Beta, IL-4, IL-5, IL-6 and IL-10 levels were found to be higher in CT-positive women with fertility disorders compared to CT-positive fertile women and controls (P < 0.05)." (PMID 19397832, 2009). "IL-10 was found to be up-regulated in cervical washes obtained from Chlamydia positive women with fertility disorders." (PMID 18828896, 2008). "When cervical washes were studied for cytokine concentrations it was seen that in Chlamydia positive women with fertility disorders significantly higher levels of IL-6, IL-8, IL-10 and IFN-γ were present compared to the other groups." (PMID 18828896, 2008). "Significantly higher levels of IL-6, IL-8, Il-10 and IFN-γ (P < 0.05) were observed in Chlamydia positive women with fertility disorders compared to Chlamydia positive fertile women and controls." (PMID 18828896, 2008). "Similarly our data suggests that IL-10 over-expression in cells from CT-positive women with fertility disorders could partly contribute to slow or non-clearance of CT resulting in establishment of tubal pathology." (PMID 19397832, 2009).
functional dyspepsia (3 papers, 2019 to 2022). "A study in H. pylori-positive patients with functional dyspepsia investigated gastric inflammatory markers and ILs (IL-4, IL-6, IL-8, IL-10, and IFN-γ) following treatment with AXT from H. pluvialis." (PMID 31248010, 2019). "In H. pylori negative functional dyspepsia patients, plasma cytokines IL-1β, IL-10, and TNF-α levels are increased compared to healthy subjects." (PMID 35527812, 2022). "In H. pylori negative functional dyspepsia patients, peripheral blood mononuclear cell mediated release of cytokines IL-1β, IL-10, IL-6, and TNF-α were correlated with intensity of pain and cramps, and also nausea, vomiting and delayed gastric emptying, which can lead to reduced food intake." (PMID 35527812, 2022). "Indeed, plasma cytokine IL-1β, IL-10, and TNF-α levels are correlated with symptom intensity of pain, cramps, nausea, and vomiting, and associated with delayed gastric emptying, in H. pylori negative functional dyspepsia patients." (PMID 35527812, 2022).
Gastrointestinal inflammation (3 papers, 2022 to 2025). Inflammation of the alimentary part of the gastrointestinal system. "Studies have revealed that the main characteristics of CAP-induced GI inflammation in mice are elevated levels of inflammatory cytokines, especially IL-10, IL-1β, and TNF-α." (PMID 35267319, 2022).
gonococcal infection (3 papers, 2019 to 2024). "Gonococcal infection in the 17-β-estradiol mouse model also induces expression of IL-10 leading to the expansion of type 1 regulatory T cells (Tr1 cells)." (PMID 37662926, 2023). "Subsequent studies found that gonococcal infection in mice also strongly enhanced the production of another regulatory cytokine, IL-10, and induced FoxP3-negative, IL-10-dependent, type 1 regulatory T (Tr1) cells." (PMID 31681305, 2019). "In a mouse model of gonococcal infection, IL-10 contributed to suppression of the Th1 response." (PMID 38704381, 2024). "Levels of IL-10 and TGF-β were also not higher in those with gonococcal infection, suggesting that a suppressive cytokine response may not be responsible for a lack of detectable pro-inflammatory cytokine response." (PMID 37662926, 2023).
gram-positive bacterial infections (3 papers, 2021 to 2022). Infections caused by bacteria that retain the crystal violet stain (positive) when treated by the gram-staining method. "When compared with healthy people, IL-6 and IL-10 were significantly increased in Gram-negative bacterial infections, while only IL-6 was significantly increased Gram-positive bacterial infections." (PMID 36590299, 2022). "Interestingly, IL-6 and IL-10 can help distinguish between Gram-negative and Gram-positive bacterial infections." (PMID 36590299, 2022).
hantavirus infection (3 papers, 2011 to 2024). "Whether hantavirus infection could trigger a similar protective IFN-induced IL-10+ ILC2 phenotype in patients remains to be further investigated." (PMID 39038044, 2024). "Strong associations of high TGF-β1 with low IL-8, IL-10 and TNF-α serum levels during acute hantavirus infection support this hypothesis." (PMID 22085404, 2011). "The regulatory T cells that produce the immunosuppressive cytokines IL-10 and TGF-β play an important role in the regulation of the immune response and limit the immunopathology induced by hantavirus infection." (PMID 28708900, 2017). "Cytokine expression of IL-2, IL-5, IL-6, IL-8, IL-10, IFN-γ, TNF-α and TGF-β1 was analysed by ELISA during the early and late phase of acute hantavirus infection (average 6 and 12 days after onset of symptoms, respectively)." (PMID 22085404, 2011). "IL-8, IL-10, IFN-γ, TNF-α and TGF-β1 in early versus late phase of acute hantavirus infection (average 6 and 12 days after onset of symptoms, respectively)." (PMID 22085404, 2011).
hemophilia A (3 papers, 2022 to 2023). The most common form of hemophilia characterized by spontaneous or prolonged hemorrhages due to factor VIII deficiency. "When the immunological profile of untreated patients with hemophilia A was assessed in comparison with the profile of healthy controls, higher levels of IL-4, IL-6, IL-8, IL-10, IL-12 and IL-17 were detected." (PMID 35186990, 2022). "Furthermore, in other bleeding disorders, such as hemophilia A (HA), the finding suggested that the level of IL-10 increased in HA patients, in comparison with that in the control group." (PMID 35145935, 2022).
hepatic granuloma (3 papers, 2012 to 2020). A granuloma located in the liver. "Nevertheless, in the present study, Treg and IL-10 augment immunosuppressive effects in hepatic granuloma of L. donovani-infected aly/aly mice." (PMID 22928057, 2012). "We found that this sensor influences the formation of hepatic granuloma, altering local chemokine (CCL2, CCL3, and CXCL1) and cytokine (IL-5, IL-10, and IL-13) production, macrophage and neutrophil recruitment into the liver, and also is important for promoting collagen deposition." (PMID 32431709, 2020).
herpesvirus infections (3 papers, 2012 to 2024). "IL10 is also known to inhibit activation of Th1 responses by suppressing the ability of antigen-presenting cells to secrete Th1-associated cytokines, which eliminate herpesvirus infection." (PMID 33499363, 2021).
histoplasmosis (3 papers, 2013 to 2022). A disease caused by the fungus Histoplasma capsulatum. "The deficiency of IL-10 conferred salutary effects on memory T cell-mediated protection to secondary histoplasmosis." (PMID 36177012, 2022). "Myeloid HIF-1α is essential for promoting antifungal immunity in a mouse model of histoplasmosis by tempering immunosuppressive interleukin-10 (IL-10)." (PMID 31036602, 2019). "Previously, we revealed a fundamental role of myeloid HIF-1α in controlling histoplasmosis by dampening the capacity of IL-10 to inhibit intracellular growth of H. capsulatum." (PMID 31036602, 2019). "In a murine model of histoplasmosis, Deepe and Gibbons demonstrated that the faster pathogen clearance in IL-10−/− mice was due to an increased biological activity of memory T lymphocytes from those mice, rather than higher cell numbers at some post-infection periods." (PMID 24205424, 2013).
hyper-IgE syndrome (3 papers, 2018 to 2023). A condition that is characterized by elevated serum IgE, dermatitis, and respiratory infections. "As shown by studies in hyper-IgE syndrome (HIES) patients, the loss-of-function mutations of STAT3 abrogates the DC responsiveness to IL-10 and thereby impairs their tolerogenic functions and ability to stimulate differentiation of CD4+ T cells to regulatory T cells (Tregs)." (PMID 29921770, 2018).
Hyperammonemia (3 papers, 2016 to 2021). An increased concentration of ammonia in the blood. "IL-10 in the plasma of hyperammonemic rats was significantly decreased after three or five weeks of hyperammonemia (59 ± 13 and 47 ± 6% of control, respectively)." (PMID 34202516, 2021). "In addition, chronic hyperammonemia also induces peripheral inflammation, increasing TNFα and decreasing IL-10 levels in the plasma." (PMID 34202516, 2021). "We have recently shown using the same animal model used here that hyperammonemia per se induces peripheral inflammation by increasing proinflammatory TNF-a, IL-6, and PGE2 and decreasing anti-inflammatory IL-10." (PMID 32087723, 2020). "Bicuculline increased IL-10 after five weeks of hyperammonemia (92 ± 10% of controls, p < 0.05) but not after three weeks (61 ± 12% of controls)." (PMID 34202516, 2021). "Sulforaphane did not restore the levels of IL-10 in hyperammonemic rats, suggesting that a minor part of the effects of hyperammonemia cannot be restored by sulforaphane or that this restoration may take a longer time." (PMID 26883214, 2016).
Hyperkeratosis (3 papers, 2022 to 2024). Hyperkeratosis is a histopathological term defining a thickened stratum corneum and may be present in many different skin conditions, with many possible overlaps. "Cumulative release at pH 7.4 and 5.8 (72 h)↓ inflammation degree and PASI, ↓ IL-17, TNF- α, TGF-β levels, ↑ IL-10 levels↓ parakeratosis, hyperkeratosis, acanthosis." (PMID 39458602, 2024).
hyperplasia (3 papers, 2020 to 2022). An abnormal increase in the number of cells in an organ or a tissue with consequent enlargement. "Hyperplasia also occurs on the stimulation of T-lymphocytes that produce several cytokines, such as IFN-γ, IL-2, IL-5, and IL-10, subsequently leading to cell proliferation." (PMID 36614420, 2022).
Hypervolemia (3 papers, 2020 to 2025). An increase in the amount of intravascular fluid, particularly in the volume of the circulating blood. "The most prominent member of the anti-inflammatory arsenal is IL-10, and in line with the theory—inflammation is followed by anti-inflammation—we confirmed an earlier observation indicating higher IL-10 mRNA expression in hypervolemia." (PMID 38612530, 2024). "How far miR-142-3p expression affects IL-6 and IL-10 regulation in hypervolemia is the subject of future studies." (PMID 38612530, 2024). "IL-10 and TIPE2 cannot balance uremic-toxin- and hypervolemia-induced inflammation." (PMID 41009490, 2025). "However, as this effect is only very small, we do not believe that AhR plays a major role in IL-10 signaling in hypervolemia." (PMID 38612530, 2024). "This may be an indication that hypervolemia does not trigger IL-10 per se." (PMID 41009490, 2025).
IgG4-related diseases (3 papers, 2022 to 2024). "There has not been a lot of research conducted involving IL-10 and neurological diseases but, in general, it looks like IL-10 should be more of a focus in IgG4-related diseases." (PMID 38473828, 2024). "In IgG4-related disease and Kimura disease, prominent IgG4 class switching is thought to be controlled by a population of Tfh cells co-expressing CXCR5, PD-1, ICOSL, IL-10, IL-4 and LAG-366,67." (PMID 39013889, 2024). "In IgG4-related diseases, IL-13-positive mast cells are increased, and IgE-positive mast cells, rather than T cells, release cytokines such as IL-4 and IL-10." (PMID 35888006, 2022).